CCL2 (C-C motif chemokine ligand 2)
Diseases named in the same sentence as CCL2 in open-access papers (continued):
Sharing a sentence is not in itself a finding about the gene and the disease.
Cerebral ischemia (continued). "In addition, many enriched inflammatory markers after cerebral ischemia, including interleukins IL-11 and IL-6, chemokines (Ccl4, Ccl2, Ccl5) and serum amyloid A (Saa3), were observed to be up-regulated consistent with reports elsewhere." (PMID 29896414, 2018). "Propofol may exhibit this neuroprotective effect in cerebral ischemia/reperfusion injury by regulating the expression levels of CCL2 and CCR2." (PMID 25009636, 2014). "Furthermore, we found that baicalin could inhibit cerebral ischemia-induced activation of the NFκB/CCL2/CCR2 pathway via targeting NFκB activation and CCL2/CCR2 interaction." (PMID 36091824, 2022). "CCL2 and CCL5 are amongst chemokines that have a dual function in the pathophysiology of cerebral ischemia." (PMID 38861234, 2025). "It has been found that after toxic acidosis, the number of activated microglia increased in brain sections of mice with cerebral ischemia, and CCL2/MCP-1 expression was significantly enhanced." (PMID 39206161, 2024). "In the CCH phase, prolonged low levels of CCL11 are detrimental to the prognosis of patients with cerebral ischemia; CX3CL1, XCL-1 and CCL2/MCP-1 exert neuroprotective effects." (PMID 39206161, 2024). "After cerebral ischemia and hypoxia, amoeboid microglia express CCL2/MCP-1 in large numbers and mediate the migration of microglia along μCP channels, leading to severe neurotoxicity and neurodegeneration." (PMID 39206161, 2024). "Protein expression levels of CCL2 and CCR2 in the hippocampus were analyzed by western blot analysis following cerebral ischemia/reperfusion." (PMID 25009636, 2014). "The results of the present study indicated that there was a synchronous increase in the expression levels of CCL2 and CCR2 in cerebral ischemia/reperfusion injury and a synchronous decrease when propofol was injected into the rats prior to surgery." (PMID 25009636, 2014). "The aim of the present study was to determine the roles of the chemotactic factor, chemokine ligand 2 (CCL2), and its receptor, chemokine receptor type 2 (CCR2), in the hippocampus of rats with cerebral ischemia/reperfusion injury." (PMID 25009636, 2014). "Expression levels of CCL2 and CCR2 mRNA in the hippocampus were analyzed by qPCR following cerebral ischemia/reperfusion." (PMID 25009636, 2014). "The monocyte chemoattractant protein (MCP-1, CCL2) and its receptor CCR2 are known to be involved in the inflammatory response of the injured brain after cerebral ischemia." (PMID 25642168, 2014). "Following cerebral ischemia, a cascade of inflammatory mediators including cytokines (TNF, IL-1α, IL-1β, IL-6, IL-10, TGFβ1) and chemokines (MCP-1 [CCL2], Mip-1α [CCL3], RANTES [CCL5]) is initiated." (PMID 22028848, 2011). "The rats with cerebral ischemia exhibited a certain weight gain after ATF3 overexpression treatment compared with MCAO‐treated rats, while the body weight of MCAO rats was downregulated again after CCL2 overexpression." (PMID 35263513, 2022). "Therefore, future research on the mechanisms underlying hypoxic-ischemic brain damage should investigate the effects of CCL2 and CCR2 using rats with cerebral ischemia/reperfusion." (PMID 25009636, 2014). "During the CI/R phase, CXCL5 recruits inflammatory cytokines at sites of cerebral ischemia and disrupts cerebral vasculature; activated cerebral vasculature can exacerbate cerebral neuronal injury by expressing CXCL13; meanwhile, XCL-1 and CCL2/MCP-1 promote neuronal apoptosis." (PMID 39206161, 2024).
liver disease (63 papers, 2004 to 2025). "This SNP is associated with increased CCL2 expression, and particular inflammatory and liver diseases." (PMID 39689089, 2024). "Infiltrating inflammatory monocytes and upregulation of CCL2 have been strongly implicated in liver disease pathogenesis based on animal models." (PMID 39568749, 2024). "A recent study reported that the overexpression of CCL2 in mice was associated with increased liver and decreased muscle weights and, as such, mimicked a phenotype frequently found in obesity, liver disease, and aging." (PMID 34356595, 2021). "Importantly, Ccl2-driven recruitment of Ly6c+ macrophages has been shown to play a role in the mechanism of fibrosis-associated angiogenesis in liver disease." (PMID 39949768, 2025). "CCL2 and its receptor display a varied expression and are closely linked with liver disease." (PMID 25528160, 2014). "Therefore, we hypothesized that levels of MCP-1 in the portal vein and hepatic transcription of CCL2 may be associated with severity of liver disease and complications of cirrhosis, including ACLF." (PMID 32218781, 2020). "Current researches have demonstrated that TNF, IL-1α/β, IL-1Ra, IL-6, IL-18, IL-33, IL-36, IL38, CCL2 and CCR2 are closely associated with liver disorders." (PMID 41333471, 2025). "CCL2 is crucial in liver diseases such as acute and chronic liver injury, cirrhosis, and tumor progression." (PMID 39850880, 2024). "In recent years, research has shown that chemokines CCL2 and IP-10 are closely related to liver diseases such as hepatitis, fibrosis, and cancer, which has attracted widespread attention." (PMID 37693903, 2023). "In liver, CCL2 plays an important role in regulating liver pathology and modulating liver disease progression." (PMID 37602516, 2023). "Among them, CCL2, as one of the key chemokines involved in liver inflammation and fibrosis, plays a crucial role in liver diseases." (PMID 37693903, 2023). "CCL2 is involved in the pathogenesis of many liver diseases, such as hepatitis, fibrosis, and cancer." (PMID 37693903, 2023). "In the early phase of liver diseases, Kupffer cell-derived proinflammatory cytokines, including CCL2, IL-1β, IL-6, IL-23, and TNF-α, induce the migration of immune cells and HSCs and contribute to the development of a proinflammatory liver microenvironment." (PMID 36380016, 2022). "In conclusion, the vital role of the chemokine ligand CCL2 in liver diseases makes it a potential therapeutic target for chronic liver disease and even HCC." (PMID 35281057, 2022). "Collectively, these studies have confirmed the essential role of the chemotactic cytokine CCL2 in the progression of liver disease, especially in the development of HCC." (PMID 35281057, 2022). "Cenicriviroc (CVC; a dual CCR2/CCR5 inhibitor) efficiently blocks CCL2 mediated monocyte recruitment and has been shown to exert anti-inflammatory and anti-fibrotic effects in various experimental liver disease models." (PMID 33868313, 2021). "What is even more compelling about hepatocyte-derived MIF controlling chemokine expression is that hepatocytes are a pivotal source of many chemokines, like CCL2 and the IL-8 family, in liver diseases, including AH." (PMID 33945507, 2021). "Being a factor with several functions, CCL2 takes part in diverse aspects of liver disease, such as cirrhosis and hepatocarcinogenesis." (PMID 32910558, 2020). "CCL2 is a multifunctional factor involved in various aspects of liver disease pathogenesis, including cirrhosis and hepatocarcinogenesis." (PMID 30894684, 2019). "The relevance of CCL2 in liver diseases was further supported by studies on liver transplantation, HCC and fibrosis regression with pharmacological inhibitor of CCL2 in mice." (PMID 25528160, 2014). "Increased CCL2 expression is correlated with disease progression and severity, as observed in pulmonary tuberculosis, HCV-related liver disease, and HIV-associated dementia." (PMID 21760952, 2011).
liver disease (continued). "The induction of CCL7 and CCL12 during fibrosis is consistent with the role of the related chemokine CCL2 in other liver diseases." (PMID 20161726, 2010). "Endothelial p300 is a regulator of gene transcription with the properties of activating NF-κB pathway, promoting CCR2+ monocytes/macrophages accumulation and increasing CCL2 expression in the damaged liver, ultimately resulting in portal hypertension and liver fibrosis." (PMID 41333471, 2025). "In the liver, CCL2 is a multifunctional regulator of liver pathology and modulates all stages of liver disease progression, from initial liver injury through inflammation and chronic hepatitis B virus (HBV)/hepatitis C virus (HCV) infection to fibrosis/cirrhosis and hepatocarcinogenesis." (PMID 35281057, 2022). "The study concluded that mice overexpressing CCL2 had an anabolic profile in the liver, with decoupling of oxidative phosphorylation components, and alterations in mitochondrial fusion; a phenomenon related to liver disease." (PMID 34356595, 2021). "CCL2 and CCL5 can recruit peripheral macrophages and T cells, a hallmark of ALF inflammation, and may play a central role in the pathogenesis of hepatic diseases, including ALF." (PMID 34877932, 2021). "Transcription levels of CCL2 in explanted livers showed a correlation to severity of liver disease." (PMID 32218781, 2020). "Following various liver diseases, hepatic and circulating chemokines, such as chemokine ligand 2 (CCL2), are elevated, though their effects on the brain following acute liver injury and subsequent hepatic encephalopathy are unknown." (PMID 25012628, 2014). "Despite these possible confinements, intriguing data from murine steatohepatitis have given proof of the generic feasibility and efficacy of CCL2 antagonism by small molecules in combating liver diseases, Clinical trials involving CCR2 antagonists in non-liver disease entities are already at hand." (PMID 23091461, 2012). "We analyzed the association between changes in plasma biomarkers and liver disease severity scores (LSM and HVPG) during the follow-up, but we only found a positive association (p-value <0.05) between plasma variations of PD1, IL10, CXCL10, CCL2, and CXCL8 and the change in LSM values." (PMID 34497613, 2021). "In addition, the pathogenic role of other chemokines such as CCL2 (MCP-1), CCL17, CCL11, CCL20 and CXCL1 in liver diseases remains unclear and requires further investigation." (PMID 32641985, 2020). "Our data show an improvement in these immune and liver disease biomarkers in plasma (immune exhaustion (PD1), chemokines (CXCL10, CCL2, and CXCL8), and cytokines (IL10)) after achieving SVR with DAA therapy in HIV/HCV-coinfected individuals." (PMID 34497613, 2021). "These chemokines such as CCL2, CCL7, CCL8, CCL11 and CCL12 were demonstrated as pro-fibrosis cytokines in liver diseases and highly expressed during our murine schistosomiasis model, and reduced more or less after PZQ treatment." (PMID 22905138, 2012). "Although a variety of chemokines have been well studied in various diseases, there is no comprehensive review presenting the roles of all known chemokine ligands of CCR2 (CCL2, CCL7, CCL8, CCL12, CCL13, CCL16, and PSMP) in liver disease, and this review aims to fill this gap." (PMID 35281057, 2022). "The CCL2/CCR2, CCL5/CCR5 and CCL1/CCR8 are very common chemoattractant axes in liver diseases." (PMID 33868313, 2021). "In addition, CCL2 has proinflammatory, profibrotic, and proangiogenic effects in chronic liver disease and tumor-promoting effects in HCC, making it a potential drug target for the treatment of liver disease." (PMID 35281057, 2022).
gastric cancer (61 papers, 2007 to 2025). A primary or metastatic malignant neoplasm involving the stomach. "The overexpression of CCL2 derived from HER2-positive gastric cancer cells caused a decrease in M1 TAMs density and recruited the M2-like phenotype of TAMs, thereby promoting resistance to trastuzumab." (PMID 39003350, 2024). "A high level of CCL2 has also been found in gastric cancer patients, and it was correlated with lymph node metastasis and reduced overall survival (OS)." (PMID 39003350, 2024). "Overexpression of CCL2 induces angiogenesis and tumorigenesis of gastric cancer cells in nude mice through macrophage recruitment." (PMID 39003350, 2024). "The abnormal expression of CCL2 has been reported in a variety of cancers, such as breast cancer, lung cancer and gastric cancer." (PMID 38057698, 2023). "In general, the low expression of CDK5RAP3 in gastric cancer can promote the secretion of CCL2, which recruits monocytes to infiltrate the tumour microenvironment through CCL2/CCR2 signalling." (PMID 35999359, 2023). "Considering that both gastric cancer cells and monocytes secrete the chemokine CCL2, we used small molecular inhibitors to explore the chemotactic function of monocytes." (PMID 35999359, 2023). "CCL2 is overexpressed in gastric cancer with low CDK5RAP3 expression, and the expression of the two is significantly negatively correlated." (PMID 35999359, 2023). "The mRNA levels of CCL2 were decreased in gastric cancer cells overexpressing CDK5RAP3 but increased in gastric cancer cells with downregulation of CDK5RAP3." (PMID 35999359, 2023). "CDK5RAP3 reduces the recruitment of circulating monocytes to infiltrate tumour tissue by inhibiting the CCL2/CCR2 axis in gastric cancer." (PMID 35999359, 2023). "CCL2 can promote drug resistance in gastric cancer cells by inhibiting autophagy, and either knockdown of CCL2 or induction of autophagy successfully reversed drug resistance in tumor cells." (PMID 35702353, 2022). "Recent studies have shown that gastric cancer-driven autocrine CCL2 activates PI3K/Akt/mTOR signaling to suppress proapoptotic autophagy, subsequently promoting sequestosome 1 (SQSTM1)-mediated CCL2 expression via NF-κB signaling." (PMID 33406733, 2021). "CCL5, CCL22, CCL21, CCL2, and CCL15 were correlated with effector memory CD4 T cell in T1/T2 stage gastric cancer, and the number of cells was associated with the expression of IL3, IL17F, IL18, IL22, and IL31." (PMID 33426088, 2020). "In immunohistochemistry of 68 patients with gastric cancer, high CCL2 expression in tumor tissue showed significantly poor prognosis." (PMID 33297571, 2020). "Tumor cells release autocrine chemokines aiding cisplatin chemoresistance by inactivating pro-apoptotic autophagy, as demonstrated by CCL2 in gastric cancer cell lines." (PMID 32499779, 2020). "Measuring chemokine levels from the plasma of 66 gastric cancer patients and 11 healthy controls revealed CCL2 levels correlated with advanced gastric cancer stage." (PMID 33297571, 2020). "A study of serum CCL2 in 78 patients with gastric cancer and 30 healthy controls showed that patients with gastric cancer with elevated serum CCL-2 levels were significantly less responsive to chemotherapy." (PMID 33297571, 2020). "As a result of examining the peripheral blood of 60 patients with gastric cancer and 20 healthy subjects, preoperative serum levels of CCL2 in patients with gastric cancer were significantly higher than those in healthy controls." (PMID 33297571, 2020). "Gastric cancer patients with high CCL2 expression also had a lower overall survival rate, suggesting CCL2 to be a prognostic marker for gastric cancer." (PMID 26885690, 2016). "In patients with gastric cancer, elevated serum and intratumoral CCL2 levels significantly correlated with lymph node metastasis." (PMID 26885690, 2016).
gastric cancer (continued). "ROC curve analysis showed that with a cut-off value of ≥1272.8, the VEGF*CCL2 predicted the presence of gastric cancer with 83% sensitivity and 80% specificity." (PMID 23697837, 2013). "In this study, we found that the serum levels of CCL2 markedly increased in gastric cancer group compared to control group." (PMID 23697837, 2013). "With a cut-off value of ≥1272.8, the VEGF*CCL2 predicted the presence of gastric cancer with 83% sensitivity and 80% specificity." (PMID 23697837, 2013). "Serum VEGF and CCL2 levels were significant independent predictors for the presence of gastric cancer." (PMID 23697837, 2013). "A large number of studies have demonstrated that CCL2 generally facilitates tumour progression where this phenomenon can be observed in pancreatic, breast and gastric cancers." (PMID 22754319, 2012). "It was reported that the knockdown of Rab5a or CCL2 could stimulate autophagy to reverse cisplatin resistance in gastric cancer." (PMID 33516270, 2021). "Moreover, CCL2 induces angiogenesis through infiltrating macrophage-derived VEGF signaling in gastric cancer." (PMID 33406733, 2021). "A study has shown that overexpression of CCL2 may be closely related to gastric diseases, which is considered to be predictive molecules of gastric cancer." (PMID 34471638, 2021). "CCL2 is additionally reported to affect the chemotherapeutic response of gastric cancer cells." (PMID 33406733, 2021). "Additionally in gastric cancer, CCL2 initiates chemoresistance to platinum drugs through PI3K/Akt/mTOR signaling pathway activation by inhibiting pro-apoptotic autophagy and increasing SQSTM1 (receptor member for autophagy) expression." (PMID 32499779, 2020). "Immunohistochemical staining of CCL2 expression in tumor tissue in 414 gastric cancer patients who underwent gastrectomy showed that the increased expression level of CCL2 was an independent prognostic factor for overall survival in patients with gastric cancer." (PMID 33297571, 2020). "Similarly, as a result of immunohistochemical examination from clinical specimens of 178 gastric cancer patients, CCL2 and Snail were independent prognostic factors of gastric cancer." (PMID 33297571, 2020). "It is also reported that tumor samples from 68 gastric cancer patients highly expressed CCL2, implied that CCL2 may have a close relationship with gastric disease." (PMID 30382864, 2018). "CCL2 expression also correlates closely with HIF-1α expression in gastric cancer." (PMID 27271610, 2016). "Macrophage infiltration was observed in both H.pylori-related gastric inflammation and gastric cancer, which was associated with overproduction of CCL2 (also named MCP-1, monocyte chemotactic protein-1), a chemokine involved in macrophage recruitment in cancer tissues." (PMID 24416340, 2014). "In a study investigating gastric cancer, researchers observed that blocking the activator receptor of MCs significantly inhibited the enrichment of MC cells and downregulated the chemokines CCL2/CCL3 in macrophages, resulting in a reduction in gastric cancer cell levels." (PMID 39456702, 2024). "In addition, coculture of gastric cancer cells with monocytes increased the secretion of CCL2." (PMID 35999359, 2023). "Moreover, it promoted the progression of gastric cancer, which was mediated by increased expression of β-TRCP and NF-κB signaling activation to produce more tumor-related cytokines such as CCL-2, IL-6, and IL-8, contributing to the development of gastric cancer." (PMID 33842314, 2021). "In addition, high levels of CCL2 were related to the inferior survival outcome in gastric cancer." (PMID 34335109, 2021). "Furthermore, CCL2 overexpression induces tumor angiogenesis via TAMs in gastric cancer." (PMID 32489462, 2020). "Thus, CCL2 is considered to be a predictive molecule for gastric carcinoma." (PMID 30382864, 2018).